IL6 (interleukin 6)
Diseases named in the same sentence as IL6 in open-access papers (continued):
Sharing a sentence is not in itself a finding about the gene and the disease.
diffuse large B-cell lymphoma (28 papers, 2017 to 2025). "Serum IL-6 and IL-2 were associated with adverse clinical features and worse outcomes in diffuse large B-cell lymphoma." (PMID 36016687, 2022). "The same study shows that loss of CD37 in neoplastic cells in patients with diffuse large B cell lymphoma (DLBCL) directly correlates with activation of the IL-6 signaling pathway and with worse progression-free and overall survival." (PMID 33333768, 2020). "A high level of IL-6 in the serum is associated with poor overall survival among patients with diffuse large B cell lymphoma." (PMID 32074125, 2020). "Notably, a subset of diffuse large B-cell lymphomas (DLBCLs) can be characterized by a polymorphism in the NF-κB1 gene, with decreased expression of the p50 monomer, and constitutive activation of the NF-κB pathway, associated with higher levels of IL-6 in patients." (PMID 39337370, 2024). "Chemoresistance in the diffuse large B-cell lymphoma (DLBCL) can be acquired by MSC secretion of IL-6 and upregulation of IL-17A." (PMID 35236376, 2022). "Hck activation can be triggered by IL‐6 in MYD88‐mutated Waldenström macroglobulinemia and diffuse large B‐cell lymphoma." (PMID 34482626, 2022). "Inhibition of HCK by A419259 blocks the activation of HCK by IL-6 and induces apoptosis in WM cells and in activated B-cell diffuse large B-cell lymphoma (ABC DLBCL) cells." (PMID 35950210, 2022). "Tumors arising in IL6-/-;Eμ-myc mice are markedly biased toward a more mature IgM+ B cell phenotype and are composed of large atypical lymphoid cells, resembling diffuse large B cell lymphoma [DLBCL], the most common non-Hodgkin lymphoma." (PMID 33651821, 2021). "For diffuse large B-cell lymphoma and non-Hodgkin lymphoma, hemoglobin < 120 g/L is a frequent sign at diagnosis, and interleukin-6 plays a vital role in its development." (PMID 28887511, 2017). "Furthermore, rituximab induces IL-6 release from diffuse large B cell lymphoma cells, which protect diffuse large B cell lymphoma cells from chemotherapy-induced apoptosis." (PMID 38530432, 2024). "Furthermore, IL-6 can provide critical intracellular signaling necessary for growth and survival of diffuse large B-cell lymphoma." (PMID 38089883, 2023). "In contrast, tumors arising in IL6-/-;Eμ-myc mice were markedly biased toward a more mature IgM+ B cell phenotype and were composed of large atypical lymphoid cells with large nuclei, resembling human diffuse large B cell lymphoma [DLBCL]." (PMID 33651821, 2021). "In B-cell lymphomas, elevated levels of inflammatory cytokines such as IL-6, IL-10, VEGF, and IL-8 have been observed in patients with diffuse large B-cell lymphoma (DLBCL)." (PMID 40292253, 2025). "Doxorubicin-induced senescence promoted the recruitment of Treg cells and myeloid-derived suppressor cells to mediate apoptotic resistance in diffuse large B-cell lymphoma (DLBCL) via pro-inflammatory cytokines, such as IL-2, IL-6, IL-8, IL-10, IL-35, TGFβ, and VEGF." (PMID 36834846, 2023). "The aim was to explore the effect of rituximab in combination with chemotherapy in treating diffuse large B-cell lymphoma and levels of vascular endothelial growth factor (VEGF), thymidine kinase 1(TK1) with interleukin-6 (IL-6), plasma T cells, NK cells as well as B cells." (PMID 40837360, 2025). "In diffuse large B-cell lymphoma (DLBCL), a subgroup called the activated B cell–like (ABC) DLBCL, are characterised by high IL-6 expression and STAT3 activity and, importantly, are selectively sensitive to JAK inhibition when compared to germinal center B-cell (GCB) DLBCL." (PMID 31226168, 2019).
gastric tumors (28 papers, 2012 to 2024). "Since inflammatory cytokines, i.e. Il-1β, Il-6 and Il-11 have been associated with development of gastric tumors, we analyzed the hyperplastic antra of Gast−/− mice for the proinflammatory cytokines." (PMID 23110168, 2012). "Gastric tumors in gp130FF mice, which harbor a knock in germline mutation in the shared IL-6/IL-11 receptor subunit gp130, arise from excessive IL-6/IL-11 dependent STAT3 activity; these tumors remain associated with chronic inflammation and immune cell infiltration." (PMID 31227713, 2019). "To further explore the relationship between IL-6 and M2 macrophage polarization we again queried the TCGA gastric tumor dataset." (PMID 38422751, 2024). "Inhibition of the JAK/STAT3 pathway in gastric tumor tissues reduces the inflammatory response, inhibits the inflammatory cytokines IL-1L, IL-6, and IL-1β, and decreases tumor volume." (PMID 34686626, 2021). "We found that levels of IL-6 were significantly higher (up to 2 times) in cancer patients than in healthy individuals and patients diagnosed with other types of gastric neoplasms." (PMID 26486258, 2015). "Our current data are consistent with these outcomes, in that WP1066 shows a strong trend to inhibit Reg1 in gastric tumours of the gp130757FF mouse along with IL-6 and IL-11 inhibition." (PMID 24804649, 2014). "In addition, a negative correlation between the expression of LOC339059 and IL-6 in gastric tumor tissues was detected via qPCR in a total of 136 GC samples (Pearson correlation r = −0.3625, n = 136, p < 0.0001)." (PMID 38001573, 2023). "Along with disease progression, glycosylation affects proteins involved in complement activation, possibly due to the host’s response to the presence of the stomach tumor, and in acute phase response signaling, possibly due to increased signaling of the pro-inflammatory cytokine, IL-6." (PMID 38069253, 2023). "Moreover, we also detected this site in a separate Stat3 ChIP experiment on gastric tumor DNA of Gp130F/F mice following a single administration of the gp130-ligand IL-6." (PMID 35053428, 2022). "Strikingly, NK cells strongly induced an inflammatory response in response to ZL-1211 treatment, including increased IFNγ, TNFα, and IL6 production, and were recruited into tumor microenvironment in patient-derived gastric tumors expressing CLDN18.2 upon ZL-1211 treatment to lyse the tumor cells." (PMID 36922936, 2022). "Both IL2‐STAT5 signaling and IL6‐JAK‐STAT3 signaling may become potential immunotherapeutic targets for low‐purity gastric tumors." (PMID 33030278, 2020). "Based on our results, future IL-6– and IL-1–targeted therapies might be expected to exert their action not only on gastric tumor cells, but also on stromal fibroblasts." (PMID 23593346, 2013). "Thus, it is probable that IL-6 derived from stromal fibroblasts promotes tumorigenesis from an early stage of the gastric tumor." (PMID 23593346, 2013). "To examine whether other immune cells such as myeloid–derived suppressor cells (MDSCs) and macrophages were also IL-6–positive cell population in the gastric tumor stroma, we performed an immunohistochemical analysis of CD11b and CD68 in the same samples." (PMID 23593346, 2013). "Next, to test whether stromal fibroblasts expressed IL-6 in this model, we performed an immunohistochemical analysis of IL-6 and αSMA in the mouse gastric tumors." (PMID 23593346, 2013). "All WT mice, but only 9/16 (56%) IL-6−/− mice, developed gastric tumors." (PMID 23593346, 2013). "On the other hand, PPAR β/δ activation causes pro-inflammatory changes in a number of systems, including IL-8 and IL1β induction in macrophages, and massive inflammatory changes in gastric tumors caused by PPAR β/δ activation, including IL1, IL6, IL24 induction." (PMID 22606335, 2012). "Up-regulation of YAP1, IL11, IL6, and STAT3 mRNA transcript expression was observed in human gastric tumor samples when compared with normal gastric tissue." (PMID 37957015, 2024).
gastric tumors (continued). "Our results confirmed that the expression of GPX4, CASP6, IL-6, CASP5, CASP4, and TIRAP was greatly up-regulated in gastric tumors relative to normal tissues." (PMID 37595258, 2023). "In summary, hypermethylation of the promoter region of the SOCS-1 gene together with high production of endogenous IL6 and TGF-β leads to hyperactivation of JAK/STAT in gastric tumors." (PMID 33569347, 2020). "IL-6 can induce M2 macrophage differentiation through STAT3 activation and can enhance infiltration of CD163+CD206+ macrophages in gastric tumor tissue." (PMID 30283449, 2018). "All gastric tumor samples, which expressed p-STAT3, also expressed IL-6 with weak expression detected in adjacent normal mucosa." (PMID 24116074, 2013). "Gastric tumours from WP1066- treated mice had reduced polymorphonuclear inflammation, coincident with inhibition of numerous proinflammatory cytokines including IL-11, IL-6 and IL-1β, as well as the growth factors Reg1 and amphiregulin." (PMID 24804649, 2014). "In addition, we observed IL-11, but not IL-6 levels, were significantly reduced in Gp130FF; Yap1KO derived tumor lysates, consistent with our previous observation that IL-11 is a key player in gastric tumor development." (PMID 37957015, 2024).
intracerebral hemorrhage (28 papers, 2013 to 2026). A cerebrovascular disorder characterized by bleeding into one or both cerebral hemispheres including the basal ganglia and the cerebral cortex. "IL-6 was produced in activated microglia and caused the brain injury after intracerebral hemorrhage under inflamed conditions." (PMID 35720096, 2022). "Both the presence of intraventricular hemorrhage and intracerebral hemorrhage (ICH) post-aneurysm rupture were associated with elevated CMD IL-6 (p = 0.003) and TNF-a." (PMID 28848487, 2017). "In murine intracerebral hemorrhage models, Cerebrolysin-treated animals exhibited significant reductions in IL-1β, IL-6, and TNF-α, as well as in aquaporin-4 (AQP4)—a main mediator of vasogenic edema." (PMID 40362194, 2025). "This should be beneficial for recovery from injury as IL-6 is necessary for the timely resolution of injury, e.g., cerebrovascular repair after an intracerebral hemorrhage." (PMID 38334617, 2024). "Intracerebral hemorrhage leads to the release of a large number of endogenous molecules, including glutamate, Ca2+, thrombin, hemoglobin, iron and IL-6, etc.." (PMID 35928572, 2022). "Through the inhibition of the TLR4/NF-κB pathway, the secretion of TNF-α, IL-6, and IL-1β decreases, and the injury to the brain due to intracerebral hemorrhage can be attenuated." (PMID 33133217, 2020). "Inhibition of microglia inflammation by reduction of NF-κB activation and by the attenuation of TNF-α, IL-1β,IL-6, and reactive oxygen species (ROS) protects the brain from intracerebral hemorrhage and MDD." (PMID 30356873, 2018). "In mouse models, both MyD88 and TRIF pathways have been implicated in regulation of IL-6 and IL-10 after cerebral ischaemia as well as regulation of IL6, TNF-α, and IL-1β following intracerebral haemorrhage." (PMID 23843682, 2013). "Previous reports also showed that IL-6 and TNF-α levels increased in TNFAIP3-/- sham groups of an intracerebral hemorrhage mouse model, suggesting that TNFAIP3 deficiency caused spontaneous inflammation in the mouse brain, which was consistent with our results in GMH pups." (PMID 32859236, 2020). "Serum IL-6 levels were found to be significantly elevated in aSAH patients presenting with higher Hunt and Hess grades, increasing age, and both intraventricular and intracerebral hemorrhage." (PMID 29194369, 2017). "Metformin downregulated the expression levels of inflammatory cytokines (IL-1β, IL-4, and IL-6 and TNF-α) in intracerebral hemorrhage model rats." (PMID 32831980, 2020). "Several clinical studies suggest that serum inflammatory factors such as IL‐6, TNF‐α, and hs‐CRP released after intracerebral hemorrhage are closely related to brain edema and brain injury." (PMID 32533644, 2020). "In the development of intracerebral hemorrhages, the expression of Toll-like receptor 4 (TLR4) is enhanced, and this could lead to an increase in the levels of TNF-α, IL-6, and IL-1β through the TLR4/NF-κB pathway, followed by aggravation of brain lesions." (PMID 33133217, 2020). "In this sense, it has been reported that endothelial progenitor cells improved the neurological function of rats with intracerebral hemorrhage by decreasing pro-inflammatory cytokines such as IFN-γ, IL-6, and TNFα, and increasing anti-inflammatory cytokines such as TGFβ1 and IL-10." (PMID 29720269, 2018).
nasal polyps (28 papers, 2010 to 2025). "IL-6 is suggested to influence the Th17 (T-helper 17) and Treg (regulatory T cells) balance that has been associated with nasal polyps." (PMID 36285981, 2022). "IL-6 mRNA was significantly increased in NP tissues of CRSwNP, revealing an increase in IL-6 in nasal polyposis." (PMID 38555391, 2024). "At the cytokine level, earlier studies investigated specific cytokines and their mechanisms in polypogenesis, reporting increased IL-6 and IL-8 levels in nasal polyps, and serum IL-16 levels were found to be elevated in patients with nasal polyposis." (PMID 38790942, 2024). "OSM and IL-6 were overexpressed in the nasal polyps when compared to the control mucosa (p < 0.0001)." (PMID 37047067, 2023). "OSM and IL-6 were both overexpressed, and TJ (ZO-1 and occludin) expression was decreased in the nasal polyps compared to the control mucosa." (PMID 37047067, 2023). "IL-6 positive structures were observed in numerous (+++) numbers in the control sample epithelium and in few (+) numbers in the nasal polyp epithelium." (PMID 36285981, 2022). "IL-7R is expressed on naive as well as memory T cells, therefore, it can be presumed that active local adaptive immune responses are taking place in the tissue of nasal polyps that are somewhat facilitated by or due to the IL-6 expression." (PMID 36285981, 2022). "IL-1α, IL-4, IL-6, IL-8, IL-10, IL-12 (p < 0.001), and Ki-67 (p = 0.001) were decreased in the epithelium of the nasal polyp samples in comparison to the control samples." (PMID 36285981, 2022). "Our findings suggest a close relationship between IL-6 and IL-7 in the epithelium as well as in the subepithelial connective tissue of nasal polyps." (PMID 36285981, 2022). "IL-1α, IL-6, IL-8, IL-10, IL-12 (p < 0.001), and IL-4 (p = 0.038) were increased in the subepithelial connective tissue of the nasal polyp samples when compared to the control samples." (PMID 36285981, 2022). "When comparing nasal polyp samples with normal mucosa from control patients, it was apparent that IL-1α, IL-4, IL-6, IL-7, IL-8, IL-10, IL-12 positive structures were significantly decreased in epithelium of the polyps." (PMID 34208325, 2021). "Considering the previously established IL-6 role in CRSwNP, it is a factor of interest when evaluating nasal polyps." (PMID 34208325, 2021). "Amount of IL-6 positive structures in nasal polyps was significantly decreased in epithelium (p < 0.001) and increased in the connective tissue (p < 0.001) in comparison to control samples." (PMID 34208325, 2021). "Like other factors, IL-6 was found significantly less in epithelium of our patients, but significantly more in connective tissue of nasal polyps when compared to controls." (PMID 34208325, 2021). "In contrast, nasal polyps revealed few to moderate IL-6 positive structures in epithelium and moderate to numerous in connective tissues." (PMID 34208325, 2021). "In contrast, another study found increased levels of IL-1β along with IL-6 and IL-8 and a high percentage of nasal polyps." (PMID 34208325, 2021). "AE in chronic rhinosinusitis with nasal polyps (CRSwNP) was associated with increased expression of mucus cytokines including myeloperoxidase (percentage increase [PI] = 101%), IL-5 (PI = 125%), and IL-6 (PI = 162%) and could be predicted by the increasing mucus cystatin and periostin." (PMID 32811568, 2020). "IL-6 was also significantly increased in the frontal recess mucosa compared with ethmoid sinus mucosa and nasal polyps in these patients." (PMID 28464955, 2017). "Messenger RNA (mRNA) levels of TGF-β, IL-5, IL-6, and iNOS in the frontal recess, ethmoid mucosa and nasal polyps were assessed by quantitative RT-PCR analysis." (PMID 28464955, 2017). "So far, a similar level of induction of IL-6, IL-8, and IL-33 in the epithelia of healthy controls and nasal polyposis patients in responses to different bacterial TLR agonists was shown with the viral analogue poly(I:C) (TLR-3 agonist)." (PMID 27050744, 2016).